MTOR (mechanistic target of rapamycin kinase)
Diseases named in the same sentence as MTOR in open-access papers (continued):
Sharing a sentence is not in itself a finding about the gene and the disease.
bone cancer (10 papers, 2017 to 2023). A primary or metastatic malignant neoplasm affecting the bone or articular cartilage. "Further research on understanding the mechanisms involved in the occurrence of bone cancer through the mTOR pathway is needed." (PMID 36428613, 2022). "Disturbances in mTOR signaling have been related to the development of malignant diseases, including bone cancer." (PMID 36428613, 2022). "It has been published that protein expression levels of p-PI3K/p-Akt/p-mTOR were increased in the periaqueductal gray of rats with bone cancer." (PMID 36428613, 2022). "Interestingly, there is a report that mTOR activation requires activation of NMDA receptors in a bone cancer-induced pain model." (PMID 28377693, 2017). "mTOR inhibition compromised CSC traits by modulating mitochondrial function in several types of cancers, such as pancreatic, ovarian, and bone cancers, suggesting that the YY1-mTOR-PGC-1α axis plays the key role in the biology of CSCs." (PMID 33728560, 2021). "Moreover, formalin-induced hypersensitivity and neuronal hyperexcitability are mediated by mTOR signaling, while the phosphatidylinositol 3-kinase (PI3K)/protein kinase B (AKT)/mTOR pathway contributes to bone cancer pain." (PMID 33806698, 2021).
brain malformations (10 papers, 2019 to 2026). "It is known that activating the mTOR pathway causes the epileptogenicity of brain malformations, specifically FCD, TS, and HS, which is supported by our finding that 80% of APEs with TSC1 or TSC2 variants had such malformations." (PMID 31875159, 2019). "Brain malformations are associated with the mTOR regulatory genes mutations as the activation of the mTOR pathway in the hippocampal neurons, elevates the branching and growth of the dendritic arbors, while their complexity was decreased in such cells by the mTOR removal in vitro." (PMID 36364000, 2022). "Gene-specific recommendations were recently reported for PIK3R1, and for AKT3, MTOR, PIK3CA and PIK3R2 by the ClinGen Brain Malformation Variant Curation Expert Panel." (PMID 38778413, 2024). "Morphologically similar brain malformations, such as HME and cortical tubers of TSC, are also associated with dysregulation of the mTOR pathway, highlighting the importance of this pathway in brain malformations." (PMID 35163267, 2022).
Crohn disease (10 papers, 2015 to 2025). A gastrointestinal disorder characterized by chronic inflammation involving all layers of the intestinal wall, noncaseating granulomas affecting the intestinal wall and regional lymph nodes, and transmural fibrosis. "Dysregulated macrophage activity is a characteristic hallmark of intestinal inflammation, especially in Crohn’s disease, while modulation of mTOR pathways is gaining popularity as a promising therapy for patients with IBD, and IL-6 and mTORC1 signaling cascades appear to be inversely correlated." (PMID 40806725, 2025). "In a murine Crohn disease model, the Met+Rap combination therapy robustly inhibited mTOR signaling and reduced inflammation." (PMID 38386420, 2024). "Additional metabolic pathways that underwent significant changes in Crohn’s disease included the mammalian target of rapamycin (mTOR) and glucose metabolism." (PMID 36131123, 2022). "mTOR activation was observed in the colon of Crohn's disease patients." (PMID 38977864, 2024). "Future studies should determine whether PPARα, PPARγ, AMPK, and mTOR modulate glycolysis in Crohn’s disease in an AhR-independent manner." (PMID 36131123, 2022).
E. coli infection (10 papers, 2017 to 2025). "To further investigate the impact of VgrG2 on the mTOR signaling pathway, we assessed the mRNA levels of key genes involved in this pathway at various time points following E. coli infection." (PMID 40266908, 2025). "Our results indicated that E. coli infection significantly modulated the expression of key genes in the mTOR signaling pathway, with VgrG2 playing a crucial role in this process." (PMID 40266908, 2025). "Collectively, these findings suggest that E. coli infection activates the mTOR signaling pathway in IPEC-J2 cells, with VgrG2 enhancing this activation." (PMID 40266908, 2025). "PBMo serve as a control and mimic the leucine effect by exhibiting an increased number of mTOR phosphorylated cells after adding leucine only, after E. coli infection and a combination of infection and leucine supplementation." (PMID 33924101, 2021). "Metabolic pathways and ribosome were the most enriched pathways, followed by the spliceosome, pathogenesis, Escherichia coli infection, endocytosis, RNA transport, the mTOR signaling pathway, and PPAR signaling, among others." (PMID 34722278, 2021). "Here, we examined in vitro whether (i) E. coli infection and leucine supplementation alter the energy metabolism in CBMo and PBMo exceedingly and (ii) whether the signaling induced by leucine and infection affects the AKT/mTOR checkpoint with comparable reactions in CBMo and PBMo." (PMID 33924101, 2021). "Surprisingly, our study showed that phosphorylations of mTOR and AKT were not decreased by Ba treatment alone or subsequent E. coli infection." (PMID 28382029, 2017).
experimental autoimmune encephalomyelitis (10 papers, 2019 to 2025). An autoimmune demyelinating disease of the central nervous system that is produced experimentally in animals by the injection of homogenized brain or spinal cord in Freund's adjuvant. "Recent study documented the role of Mid-1 in regulation of T cell entrance to the CNS in a model of experimental autoimmune encephalomyelitis and the ability of Mid-1 to affect mTOR signaling in T lymphocytes." (PMID 40443734, 2025). "Overexpression of miR-99a, that is frequently down-regulated in RA and SLE, mitigated the development of experimental autoimmune encephalomyelitis (EAE) in mice through the inhibition of mammalian target of rapamycin (mTOR)-dependent glycolysis." (PMID 38339220, 2024). "In experimental MS models, rapamycin with mTOR inhibition can prevent the clinical course of both relapsing-remitting and chronic experimental autoimmune encephalomyelitis, suggesting important clinical applications for the treatment of MS." (PMID 37508898, 2023). "There is robust evidence that mTOR inhibitors, such as rapamycin, ameliorate the clinical course of the animal model of MS, experimental autoimmune encephalomyelitis (EAE)." (PMID 35897651, 2022). "Also, rapamycin—an immunosuppressant drug that inhibits mTOR by destabilizing the mTOR–Raptor complex—controls disease progression in experimental autoimmune encephalomyelitis (EAE) mice by suppressing Teff cell functions." (PMID 31555261, 2019).
facial angiofibroma (10 papers, 2008 to 2025). "There have been several trials illustrating the clinical efficacy of topical mTOR inhibitors for the treatment of incurable facial angiofibroma associated with TSC." (PMID 35453576, 2022). "This is a retrospective study of TSC Alliance’s Natural History Database aimed to characterize facial angiofibroma and to evaluate features associated with a higher risk of facial angiofibroma or the use of topical mTOR inhibitors for the management of facial angiofibroma." (PMID 36104799, 2022). "Use of systemic mTOR inhibitors have shown ancillary improvement of facial angiofibroma during therapy for other manifestations." (PMID 40855504, 2025). "Topical mTOR inhibitors reduced the size and improved the color of facial angiofibroma in multiple clinical trials and case reports, which was maintained over time, and was further confirmed in a post marketing surveillance conducted in Japan." (PMID 40855504, 2025). "Facial angiofibroma was seen in 23% of adults and 30% of children and topical mTOR is being prescribed." (PMID 39165678, 2024). "A total of 593 (44.6%) patients were not receiving any treatment for the management of facial angiofibroma or noted for systemic mTOR inhibitor use for facial angiofibroma or other TSC manifestations." (PMID 36104799, 2022). "About one-fourth of patients with facial angiofibroma used a topical mTOR inhibitor and use of systemic mTOR inhibitor for the management of facial angiofibroma or for the other manifestations was noted for 30.0%." (PMID 36104799, 2022). "Various topical formulations of the mTOR inhibitor sirolimus (rapamycin) are effective and generally well tolerated for the management of facial angiofibroma based on several short-term studies, which was further established over the long term." (PMID 36104799, 2022). "Systemic everolimus (mTOR antagonist) is another drug that effectively reduces or prevents the growth of subependymal nodules and improves skin lesions like facial angiofibroma." (PMID 35600170, 2022). "Of the patients with facial angiofibroma, 399 (30.0%) patients received systemic mTOR inhibitors for the management of facial angiofibroma or for other TSC manifestations." (PMID 36104799, 2022). "Use of systemic mTOR inhibitor for facial angiofibroma was noted for 163 (12.3%) patients, among whom only 9 (0.7%) patients used exclusively for the management of facial angiofibroma." (PMID 36104799, 2022). "Studies with oral mTOR inhibitors showed concurrent improvement in facial angiofibroma and other TSC skin lesions." (PMID 36104799, 2022). "A total of 163 (12.3%) patients received an mTOR inhibitor for the management of facial angiofibroma, however, only 9 (0.7%) patients received systemic mTOR inhibitors exclusively for the management of facial angiofibroma." (PMID 36104799, 2022). "To assess the effects of topical mTOR inhibitors in treating facial angiofibromas, we conducted a systematic review and network meta-analysis (NMA) and searched MEDLINE, Embase, and Cochrane Library for relevant randomized controlled trials on 14 February 2022." (PMID 35453576, 2022). "Topical mTOR inhibitor was used by 329 (24.8%) patients for the management of facial angiofibroma." (PMID 36104799, 2022). "Topical mTOR inhibitor use was noted for one-fourth of patients with facial angiofibroma." (PMID 36104799, 2022). "Topical mTOR inhibitor use was noted for 329 (24.8%) patients with facial angiofibroma." (PMID 36104799, 2022). "Topical formulations of mTOR inhibitors have the potential to improve facial angiofibroma related to TSC without systemic exposure and associated side effects." (PMID 36104799, 2022). "It is likely that activated mTOR is also present in some TSC skin lesions because loss of heterozygosity for TSC2 has been demonstrated in a facial angiofibroma and tuberin and/or hamartin are absent in many facial angiofibromas from individuals with TSC." (PMID 18226258, 2008).
facial angiofibroma (continued). "Systemic mTOR inhibitors are used to treat multiple manifestations of TSC, however, their use for the treatment of facial angiofibroma specifically would be off label." (PMID 40855504, 2025). "Based on the strong evidence for the effectiveness and safety of topical mTOR inhibitors in the management of facial angiofibroma, topical sirolimus is recently approved by the FDA for the management of facial angiofibroma in the United States." (PMID 36104799, 2022). "However, oral mTOR inhibitors are not approved by regulators for treatment of facial angiofibroma as there could be increased risk of systemic side effects associated with an immunosuppressive effect of these drugs." (PMID 36104799, 2022). "However, side effects associated with systemic exposure to mTOR inhibitors may not justify its use solely for the treatment of facial angiofibroma in most cases." (PMID 36104799, 2022). "Despite the lack of FDA-approved topical mTOR inhibitor in the United States at the time of survey, use of compounded topical rapamycin for the management of facial angiofibroma was reported by 105 (31.3%) caregivers and 23 (23.5%) patients with TSC." (PMID 40855504, 2025). "In the Natural History Database, 44.6% of patients with facial angiofibroma did not receive any treatment for the management of facial angiofibroma, and about one-fourth of patients were treated with off-label, compounded topical mTOR inhibitors for the management of facial angiofibroma." (PMID 36104799, 2022).
infarction (10 papers, 2018 to 2025). A localised pathological necrosis of tissue resulting from obstruction of the blood supply usually by a thrombus, an embolus, or vascular torsion. "IR hearts with activation of the PI3K-AKT-mTOR axis exhibited beneficial phenotypes, including reduced infarction, lower apoptosis rates, and higher myocardial ATP contents, compared with those in IR hearts without mTOR activation." (PMID 37942483, 2023). "Tolerogenic DCs, which are likewise boosted by mTOR inhibition may contribute to promotion of regulatory T cells and subsequently preserved cardiac function after infarction." (PMID 35845058, 2022). "TTC staining has been performed to evaluate the effects of mTOR inhibitors on brain infarctions in the TBI, revealing an increased necrotic tissue area in TBI mice compared to sham group; treatments with rapamycin and KU0063794 significantly attenuated the lesion area following TBI." (PMID 34245104, 2021). "PRAS40 is a link between the Akt and the mTOR pathway, and our previous study suggests that PRAS40 KO enlarges infarction while the overexpression of PRAS40 by lentiviral vector gene transfer inhibits brain injury." (PMID 32832192, 2018).
left ventricular hypertrophy (10 papers, 2009 to 2023). Enlargement of the LEFT VENTRICLE of the heart. "The protein kinase B (AKT)/FOXO3 and AKT/mammalian target of rapamycin (mTOR) pathways have been implicated as potential mechanisms involved in the regulation of left ventricular hypertrophy (LVH) induced by pressure overload." (PMID 38074330, 2023). "In addition, MEF2C deficiency alleviated the left ventricular hypertrophy induced by pressure overload through regulating the mTOR/S6K pathway in mice." (PMID 33817315, 2021). "Mef2c silencing alleviates pressure-induced left ventricular hypertrophy by modulating the mTOR/S6K pathway." (PMID 37221368, 2023). "MEF2C silencing attenuated load-induced left ventricular hypertrophy by modulating mTOR/S6K pathway in mice." (PMID 34054926, 2021). "Ma Z, Qi J, Meng S, Wen B, Zhang J. Swimming exercise training-induced left ventricular hypertrophy involves microRNAs and synergistic regulation of the PI3K/AKT/mTOR signaling pathway." (PMID 34320083, 2021).
lung NETs (10 papers, 2015 to 2024). "The phase III RADIANT-4 trial evaluated the efficacy of everolimus (mTOR inhibitor) in comparison to placebo in patients with advanced, well-differentiated, G1/G2 gastrointestinal and lung NETs." (PMID 35326587, 2022). "The expression levels of mTOR gene and mTOR-targeting miRNAs were clearly different between the histologic subtype of pulmonary neuroendocrine neoplasms." (PMID 29938004, 2018). "An Italian study on mTOR pathway in lung NETs highlighted the activation of mTOR (by means of IHC for Ser2448 phosphorilated-mTOR, p-mTOR) and pS6K in TCs and ACs." (PMID 29509701, 2018). "Apparently, chloroquine suppresses tumor cell growth in lung neuroendocrine neoplasms models, potentiating the effects of the mTOR inhibitors, and implying that more research is warranted to unravel its possible role in the clinical setting, in patients with advanced lung neuroendocrine neoplasms." (PMID 34944946, 2021). "In fact, an mTOR inhibitor, everolimus, has demonstrated antiproliferative activity in these neoplasms and is approved for the treatment of advanced gastrointestinal, pancreatic and lung NETs." (PMID 34072010, 2021). "Seven miRNAs, selected by bioinformatic tools and literature search, were analyzed in 142 lung neuroendocrine neoplasms (92 carcinoids and a control group of 50 high grade neuroendocrine carcinomas), and compared with mTOR mRNA expression and clinical/pathological parameters." (PMID 29938004, 2018). "Concerning the mechanisms leading to mTOR pathway deregulation, molecular alterations in oncogenes and tumor suppressor genes that are members of the pathway were recently found in lung neuroendocrine neoplasms, but with a relatively low prevalence in carcinoids." (PMID 29938004, 2018). "According to an in vitro study, mTOR inhibition may be effective in the treatment of pulmonary neuroendocrine tumors." (PMID 26798346, 2015). "Everolimus, a mTOR inhibitor, is currently approved for the treatment of GEP and lung NETs." (PMID 39199391, 2024). "However, no improved overall survival was observed in p-mTOR-positive tumors, neither in low grade nor high-grade lung NETs." (PMID 29509701, 2018).
muscular atrophy (10 papers, 2016 to 2025). "Mammalian targeting of rapamycin (mTOR) inhibitors sirolimus and everolimus can also cause muscular atrophy by inhibiting the Akt/mTOR pathway that regulates skeletal muscle hypertrophy." (PMID 34575704, 2021). "To further understand the underlying molecular mechanism of Nob in the treatment and prevention of skeletal muscle atrophy, we examined the protein synthesis signaling pathways (mTOR/Akt) in the CK, D-gal, and D-gal + Nob groups." (PMID 37111020, 2023). "It is reported that mTORC1 is activated in denervation-induced skeletal muscle atrophy and further downstream activation of MAFbx and MuRF1 to promote atrophy, but the anti-atrophy effect of mTOR inhibition by rapamycin treatment was inconclusive." (PMID 27462398, 2016). "In addition to the regulation of myoblast proliferation via p21, Mstn also regulates protein synthesis via the Akt/mTOR pathway by inhibiting the phosphorylation of AKT leading to muscular atrophy." (PMID 36060799, 2022). "However, the major drawback of DEX usage causes depression via the modulation of cellular glucose metabolism and AMPK/mTOR signaling pathways; alterations in the vascularization process via the modification of progesterone receptor actions; and enhances muscular atrophy." (PMID 37242430, 2023). "Muscular atrophy and weakness are common symptoms in all forms of ALS, suggesting a potential role for mTOR in the neurodegenerative pathophysiology." (PMID 40299664, 2025). "Mice lacking raptor, a component of mTOR, suffer premature death due to significant muscular atrophy and decreased body weight." (PMID 40299664, 2025). "Modulation of mTOR activity has been reported in Pompe disease, the first LSD to be biochemically characterised, where the significant muscular atrophy can be ameliorated by experimental induction of mTOR, which leads to substantial clearance of autophagic debris." (PMID 34831346, 2021). "Although our study focused on the Akt/mTOR/FoxO3a pathway, future research should examine whether SGE and kirenol also influence these pathways, which could provide a more comprehensive understanding of their therapeutic effects in skeletal muscle atrophy." (PMID 41019176, 2025).